CD4 (CD4 molecule)
Diseases named in the same sentence as CD4 in open-access papers (continued):
Sharing a sentence is not in itself a finding about the gene and the disease.
tumor (continued). "In a study by Kimura and Okuda investigating metastatic lung carcinoma, they found that resveratrol significantly reduced tumor volume, weight, and lung metastasis only at high doses (2.5 and 10 mg/kg) without affecting the number of CD4+ (helper), CD8+ (cytotoxic), and NK-cells in the spleen." (PMID 34174798, 2022). "Indeed, Bos and Sherman have demonstrated that specific CD4+ T cells promote tumor eradication compared to non-tumor-specific CD4+ help during CD8+ priming." (PMID 35008422, 2022). "All various subsets of effector T cells may be found in the tumor microenvironment (TME) including Th1, Th2, Th9, Th17, Tregs, CD4+ CTL and T follicular helper cells (Tfh) and can be located in the core of the tumor and the invasive margin or the adjacent TLS forming the tumor immune contexture." (PMID 35008422, 2022). "Finally, GINS4 was positive correlated with tumor purity (r = 0.148, p = 2.06e-02), and negative correlated with the levels of tumor-infiltrating CD4+ T cell (r = −0.175, p = 6.57e-03)." (PMID 36092720, 2022). "Interestingly, CD4+ T-cell infiltration in the stroma, but not in the tumor parenchyma, correlated with the number of Meflin+ CAFs in patients with NSCLC." (PMID 35236758, 2022). "To investigate this, we compared helper CD4 positive (CD4+) and cytotoxic CD8 positive (CD8+) T cell infiltration via immunohistochemistry in patient-derived primary tumors, lymph nodes involved by tumor metastasis, and uninvolved peri-tumoral colonic tissues between men and women." (PMID 36387163, 2022). "Initially, the presence of CD4 and CD56 should be evaluated since only 8% of BPDCNs are negative for these, and their mere presence without other specific lineage markers such as CD19, cCD3, MPO, CD14, or CD64 with high HLA-DR should alert about the possibility of this type of neoplasm." (PMID 35530883, 2022). "In this model, B6 mice were injected subcutaneously with B16-OVA tumor cells and then treated 10 days later with either naïve OT-I CD8+ T cells, aAPC-activated OT-I CD8+ T cells, or OT-I CD8+ T cells co-activated with Th1 OT-II CD4+ T cells using MHC I + II aAPCs." (PMID 36241639, 2022). "Therefore, optimal efficacy in these models correlated with an increase in activated, memory and proliferating CD4+ and CD8+ T cells in the blood, TDLNs and tumor, an increase in cytotoxic NK cells and a reduction in Treg and exhausted CD8+ T cells in the tumor microenvironment (TME)." (PMID 35256819, 2022). "In HCC patients with complete or partial tumor response to TACE, the levels of circulating Th1, Th17 and CD4+/IFN-γ+/IL-17+T cells increased, suggesting that Th17 is closely related to liver cancer, and may have the “dual identity” of tumor-promoting and anti-tumor effects at the same time." (PMID 35965593, 2022). "Additionally, we found that PNET metastatic sites were significantly enriched with cytotoxic CD8+ T cells, and the CD4/CD8 ratio of T cells isolated in metastatic sites were skewed from its ratio observed in peripheral blood, indicative of a tumor-driven immune response." (PMID 36301668, 2022). "In addition, heterotopic tumors from CreERT2 mice showed diminished inflammation demonstrated by reduced presence of total leukocytes (CD45+ area), TAMs (CD68+ area), neutrophils (MPO+ cells), tumor-infiltrating lymphocytes, TILs (FOXP3+), as well as T regulatory cells, Tregs (FOXP3+CD4+ cells)." (PMID 35688943, 2022). "Furthermore, CCR4 was significantly correlated with tumor infiltration of B cells, CD8+ T cells, CD4+ T cells, and macrophages, while TMCO1 was significantly correlated with CD8+ T cells, and SPACA4 was significantly correlated with B cells, CD8+ T cells and Neutrophils." (PMID 36671475, 2022). "Further, we investigated the levels of T‐cell infiltration in tumour tissues using IHC analysis that showed the immune infiltration of CD3, CD4 and CD8 in DCZ0415‐treated tumours indicating that the infiltration of T cells could be leading to tumour regression in mice." (PMID 35194944, 2022).
tumor (continued). "The underlying mechanisms are not clear yet, nevertheless, these data indicated that CD4+ T cells might hold potential for long-term tumor control." (PMID 35928827, 2022). "However, CD4+ T cells have attracted attention in the field because they are not only crucial for promoting CD8+ T cell functions, preventing CD8+ T cell depletion or inducing CD8+ T cell memory, but also able to directly or indirectly kill tumor cells." (PMID 35681453, 2022). "In this study, we found that NOP14 expression levels were positively correlated to the infiltration levels of numerous immune cells, such as CD8 cells, CD4 cells, NK cells, and dendritic cells, suggesting that NOP14 might promote the anti-tumor immune response in tumor tissues." (PMID 35473611, 2022). "Gal-9 expression on TILs was significantly correlated with CD4 on TILs (P = 0.025), CD8 on TILs (P = 0.001), FOXP3 on TILs (P = 0.022), OX40L on tumor cells (P = 0.03), OX40L on TILs (P = 0.00018), PD-1 on TILs (P = 0.002), PD-L1 on tumor cells (P = 0.026), and PD-L2 on tumor cells (P = 0.048)." (PMID 36263183, 2022). "Stratification of the ER+ tumor samples by miR-18a levels in the TCGA and METABRIC cohort and immune cell identification performed using CIBERSORT and Immune CellAI algorithms revealed a higher proportion of T-regulatory cells (p < 0.001) and a higher CD4/CD8 ratio (p < 0.01)." (PMID 35626709, 2022). "In general, chemotactic genes that correlated positively or negatively with CD8+ T cells consistently showed the opposite correlation with Treg or CD4+ memory T cells, suggesting that distinct chemotactic pathways could control CD8 T cell vs immunosuppressive Treg tumour recruitment." (PMID 35301339, 2022). "This method likely allows for the presentation of MHC-II-restricted tumor antigens that may not normally be presented to CD4+ T cells, and this could be responsible for eliciting the cytotoxic CD4+ T cells in this treatment paradigm." (PMID 36159781, 2022). "This was not the case for CD4+ CAR T cells targeted at BCMAlow tumor cells." (PMID 35821635, 2022). "Besides, the infiltrations of 19 types of immune cells were significantly higher in the low-risk groups compared to the high-risk group, including some immune cells that played crucial role in tumor immunity such as CD8 T cells, CD4 T cells, natural killer cells and B cells." (PMID 36451085, 2022). "Thus, CD4+ and CD8+ T cells are the core of anti-tumor immunity research." (PMID 35646934, 2022). "Although comparable activation status of CD4+ and CD8+ T cells in lung tissues and lung tumors in both groups, there is a remarkable reduction of tumor infiltration of T cells by B cell depletion, resulting in a net inhibition of T cell immunity in tumor microenvironment." (PMID 36249034, 2022). "Likewise, T cell content (CD4- or CD8-positive cells) in the primary tumor did not significantly differ at any timepoint by host genotype even as tumors continued to expand during this period." (PMID 35727842, 2022). "However, the ratio of CD4+/CD8a+ T cells was lower in both PLD and PLAD treated mice, which may be indicative of less immunosuppression in the tumor microenvironment." (PMID 36105861, 2022). "To further corroborate the relationship between CD4 T-cell activation and tumor burden, we performed an unbiased correlation analysis of all the treated tumor samples for tumor burden and CD4 T IFNγ+ cell frequency and found a strong negative correlation between these two parameters." (PMID 35651802, 2022). "Furthermore, TIICs, including activated CD8 and CD4 T cells, effector memory CD8 T cells, and type 17 Th cells, were enriched in the low-m5C-score subgroup, whereas the infiltrating levels of pro-tumor immune cells (plasmacytoid dendritic cells) were significantly higher in the high-m5C-score group." (PMID 36532062, 2022). "However, in all tumor types GITR expression was highest on CD4+ and CD4+ FoxP3+ TIL." (PMID 36155259, 2022).
tumor (continued). "Tumor rejection, however, is not the universal outcome of CD4/TAM interactions." (PMID 35903540, 2022). "Phenotypic analysis of primed splenocytes from a mixed culture with DC unstimulated with tumor antigens do not show a significant increase in the percentage of CD4+, CD4+ T cells, and NK cells as well as in the percentage of cells expressing CD107a molecules on their surface." (PMID 35372586, 2022). "The purpose of staining was to observe the infiltration of CD3+ T cells, CD4+ T cells and CD8+ T cells in STAD tumour tissues and surrounding tissues to determine whether the high expression of CHSY3 in TIME is consistent with the characteristics of immune evasion." (PMID 35571047, 2022). "Likewise, treatment with the combination of IL-5 and GM-CSF blocking antibodies did not reverse the tumor-suppressing function of WT CD4+ T cells in Tslptg TslprKO mice." (PMID 35657353, 2022). "Moreover, previous studies have revealed that the anti‐tumor function of CD4+ T cells is not weaker than that of CD8+ T cells." (PMID 35179267, 2022). "Flow cytometry analysis of subcutaneous tumours treated with anti-CTLA-4or anti-PD-1 demonstrated that only anti-CTLA-4 treatment effectively depletedFoxp3+ Tregs,resulting in an increase in the ratio of CD8+ and CD4+effector T cells to Tregs, as previously reported." (PMID 35930804, 2022). "To better understand the relationship between TLSs and the tumor microenvironment, we explored the general composition of TLSs in ESCC patients using traditional IHC in serial sections stained for CD45+ lymphocytes, CD20+ B cells, CD4+ T cells, CD8+ T cells, and CD11c+ DCs." (PMID 35711130, 2022). "CCR10 and its ligand CCL28 are known to participate in the recruitment of tumor TReg lymphocytes, and a decrease in CD4+ CCR10+ cells may reflect a reduced global presence of CCR10-expressing TRegs and, therefore, a reduced recruitment of these cells by the tumor." (PMID 35740564, 2022). "The finding that these Th cell–APC interactions occur in the tumor stroma, coupled with evidence for enrichment in Tfh cell content among the PD-1+ICOS+CD4+ TIL cohort, suggests that these lymphoid aggregates may represent one of the various maturational stages of TLSs." (PMID 35703176, 2022). "The importance of CD4+ T cells in tumor rejection was demonstrated by the fact that none of the vaccinated CD4 knockout mice rejected the challenge tumor, while all vaccinated wild-type mice did, and a significant portion of the CD8 knockout mice was able to reject the challenge tumor." (PMID 36159781, 2022). "IL-17 also acts as tumor suppressor during the process of tumorigenesis by enhancing NK cell and CTL cell activation, and recruiting neutrophil, NK cell, CD4+ and CD8+ T cell infiltration into tumor tissues, hence, reduced levels of IL17 may favor the development of cancer lesions." (PMID 35804391, 2022). "Upon activation, CD4+ T cells could differentiate into CD4+ helper T cells, secrete IL-2 to activate CD8+ cytotoxic lymphocytes (CTLs), which take essential roles for killing tumor cells." (PMID 35712476, 2022). "The involved cell types include T cells (γδ T cells, and CD4+ and CD8+ αβ T cells), B cells, NK cells, dendritic cells, monocytes/macrophages, neutrophils, endothelial cells, fibroblasts, eosinophils, basophils), tumor cells, and pathogen cells (e.g., viruses, bacteria, and parasites)." (PMID 35185886, 2022). "The tetanus toxoid induced attraction of CD4 T cells, with increased production of IFNγ, perforin, and granzyme B in the TME, while gemcitabine was used to reduce immune suppression in the TME, which resulted in reduced tumor burden by 80% compared to untreated mice." (PMID 35757741, 2022). "Infiltrating CD45+CD3+CD4+ and CD45+CD3+CD8+ T cells were more abundant in Gata4-activated tumors than controls, and the increase was dose-dependent, suggesting that there is a minimum number of Gata4-expressing cells necessary in a tumor to achieve maximal tumor suppression." (PMID 35017504, 2022).
tumor (continued). "Intensive B cell marker staining and CD4+ TFH markers colocalized with PD-1T TILs, implying that CD8+PD-1T TILs might recruit CXCR5+ B cells and TFH cells into the tumor region and that B cells, as well as TFH cells, could reinforce the antitumor capacity of CD8+ T cells." (PMID 35053457, 2022). "Moreover, the tumor-derived TGF-β was shown to inhibit mitochondrial respiration and suppress IFN-γ by CD4+ cells, suggesting that TGF-β1 may play a key role in mediating the inhibitory effects of CM on LECs." (PMID 35806196, 2022). "The levels of essential immune cells for antitumor immunity, such as CD4+ T cells, CD8+ effector T cells, and NK cells, were increased by L. lactis GEN3013 administration compared to those obtained via control IgG treatment in both the spleen and tumor microenvironments." (PMID 36077619, 2022). "Targeting antigens for macroautophagy in medullary thymic epithelial cells via fusion with LC3B, a strategy that has been used to increase MHC class II presentation for a variety of viral and tumor antigens, leads to negative selection of CD4+ T cells that are specific for the respective antigens." (PMID 35309359, 2022). "Altogether, these results show that MHC-II can be induced in tumor cells resistant to IFN-γ by co-treatment with inhibitors, which could ultimately turn MHC-II-negative into MHC-II-positive tumors and, therefore, potentially targetable by CD4+ T cell therapy." (PMID 35655709, 2022). "To summarize, our results suggest that certain CAF-derived soluble factors downregulated the expression of CXCR3 on CD4+ and CD8+ T cells and CCR5 on CD8+ T cells and upregulated the expression of CXCR4 on CD4+ and CD8+ T cells, which affect their migratory capacity towards tumor cells." (PMID 35954489, 2022). "We also showed that CAF-derived soluble factors downregulated the expression of CXCR3 on CD4+ and CD8+ T cells and CCR5 on CD8+ T cells and upregulated the expression of CXCR4 on CD4+ and CD8+ T cells, potentially affecting their migratory capacity towards tumor cells." (PMID 35954489, 2022). "Consistent with previous findings, IS4 and IS5 were associated with low infiltration of activated CD4 T cells, gamma delta T cells, CD56 bright natural killer cells, and activated DCs, indicating the absence of immune cells in the tumor microenvironments of IS4 and IS5." (PMID 35874675, 2022). "However, both CD39 and PD-1 are also expressed by regulatory CD4+ T cells (Tregs), and CD69, rather than CD103, is a marker of tumor residency in CD4+ T cells." (PMID 36003398, 2022). "Because the tumor microenvironment influences the TIL response, it will be important to further characterize the TILs for both antitumor and suppressive phenotypes and quantitate the ratios of activated CTLs (CD8+ICOS++) versus TRegs (CD4+FOXP3+) posttreatment." (PMID 35094188, 2022). "In aspect of cancer immunity, Tumor Immune Estimation Resource algorithm showed that the expression of TEAD family members was obviously related to multiple of infiltrating immune cells including macrophages, neutrophils, dendritic cells, B cells, CD8+ T cells and CD4+ T cells." (PMID 35077390, 2022). "Additionally, interdigitating DCs and tumor cells overexpress indoleamine 2,3-dioxygenase (IDO) that is known to prevent immune-mediated rejection of the tumor cells, block CD8+ T cells proliferation, and favor CD4+ apoptosis." (PMID 36298472, 2022). "Thus, our data are consistent with ICOS being an important target to identify both CD8 and non-Treg CD4 T cells with the potential to participate in tumor control." (PMID 36056093, 2022). "Furthermore, n=9 neoantigen-specific TCR clonotypes that were shared with tumor tissue were also detected in the blood ex vivo, including n=1 (CD8) and n=6 (CD4) clonotypes for POC1B MUT and n=2 (CD4) clonotypes for MAFF MUT; no WT-specific TCR clonotypes were observed in the blood ex vivo." (PMID 35361728, 2022).
tumor (continued). "In addition, the ratio of CD4+CD25+Foxp3+ cells may be correlated with immune tolerance and tumor cell survival." (PMID 35181676, 2022). "CD4+CD25+ regulatory T cells are proved to suppress antitumor response and result in tumor immune escape, while non-regulatory CD4+ helper T cells may be beneficial to the host defense against tumor." (PMID 35506372, 2022). "Our analysis demonstrated that LY96 was positively correlated with tumor-promoting immune cells, including M1 macrophages and T cell regulatory Tregs, whereas high LY96 expression was negatively correlated with tumor immune suppression cells, including activated CD4 memory T cells and CD8 T cells." (PMID 35647025, 2022). "We speculate that the insufficient tumor control, despite elevated CD8+ T cell and NK cell ratios, might be due to insufficient cytokine support of immunocompetent effector cells, which is induced by a reduced prevalence of CD4+ T helper cells." (PMID 36428793, 2022). "However, the invasive margin of tumor tissue in encapsulated metastases did not demonstrate enrichment of these immune cell subsets, and conversely, showed a lower density of CD4+ positive lymphocyte subsets and CD45R0+ cells." (PMID 35158957, 2022). "These novel CD4+CD69+FOXP3− Tregs accounted for the vast majority of tumor‐infiltrating Tregs compared with FOXP3+ Tregs and could suppress the CD4+ T‐cell response mainly through mTGF‐β1,145, 146 which was correlated with tumor progression." (PMID 35474948, 2022). "Additionally, the differentiation of T-lymphocyte profiles in cSCC has shown that moderately and poorly differentiated cSCC had a higher PD-1/PDL-1 expression that correlated with an increased number of CD4+, CD8+, CD4+ FOXp3+ regulatory T cells and enhanced tumor invasiveness." (PMID 35463364, 2022). "Notably, the frequency of GrB+CD4+ T cells did not correlate with anti-tumor response and in fact was negatively correlated among the CD8+ T cells." (PMID 36419897, 2022). "A recent study characterizing the TCR repertoires of TI-Treg cells in human metastatic gastrointestinal melanoma, and ovarian cancers showed a significant overlap with circulating Treg cells but not with conventional CD4+ T cells found in either tumor or blood." (PMID 35874729, 2022). "To further delineate the contribution of the host immune response to the anti-tumor effect of combination therapy, we treated tumor-bearing mice with depleting anti-CD4, CD8, NK1.1, or IFN-γ antibodies to eliminate, respectively, CD8+ T cells, CD4+ T cells, NK cells, and IFN-γ." (PMID 36365247, 2022). "Interestingly, although CD4+ CAR-T cells are slower than CD8+ CAR-T cells for instigating target cell death, the single-cell analysis revealed that these cells achieved the same degree of tumor cell death." (PMID 35154479, 2022). "Tretinoin is also a powerful regulator of Treg activity and can induce Foxp3 expression in peripheral CD4+ T cells, converting them to Tregs as well as increase the number of tumour infiltrating Tregs, although we saw no changes to CD4+ Treg and non-Treg populations." (PMID 35402250, 2022). "Activin A secreted from melanoma cells also hindered proinflammatory signaling of cytokines and chemokines and shifted the composition of tumor immune infiltrates in the tumor microenvironment from CTLs and NK to increased non-regulatory cells such as CD4+ T cells, DCs, and monocytes." (PMID 36353620, 2022). "Studies have reported that a decrease in the CD4+/CD8+ ratio is related to the occurrence of a variety of malignant tumors, but in this study, we came to the opposite conclusion, which indicates that the role of CD4+CCR5+ T cells is completely opposite to that of tumor-infiltrating lymph node cells." (PMID 36033472, 2022).